CTLA4 (cytotoxic T-lymphocyte associated protein 4)
Diseases named in the same sentence as CTLA4 in open-access papers (continued):
Sharing a sentence is not in itself a finding about the gene and the disease.
infection (continued). "CTLA-4 expression correlates positively with disease progression and negatively with the capacity of CD4+ T cells to produce interleukin 2 in response to viral antigen, and consequently to clear the infection." (PMID 34571876, 2021). "Blockade of PD-1 and CTLA-4 and abrogation of IL-27R signaling thus raised the level of T-bet within the overall CD4+ T cell population, and this directly correlated with an increase in CD4+ T cell glycolytic metabolism during infection." (PMID 32817333, 2020). "Surprisingly, expression of PD1 was largely unchanged, and no long-term difference in expression of CTLA4 was observed on antigen-experienced CD4 or CD8 cells in mice that received all three infections compared with mice that received mock infections." (PMID 29963060, 2018). "Skin pigmentation was seen in most of the infection sites, with the exception of three mice receiving CTLA4 Ig and one receiving anti-TNF that never developed skin necrosis." (PMID 28264025, 2017). "CTLA4 expression by CD4+ T cells was higher in patients who developed culture positive infections compared to noninfected patients (P = .04)." (PMID 28363639, 2017). "More globally, subjects with neuroinvasive infections had reduced numbers of CD4+FoxP3+ Tregs that were CTLA4 positive and exhibited a distinct upregulated transcript profile that was absent in subjects with asymptomatic infections." (PMID 26795118, 2016). "An increase in CTLA-4 mRNA expression was observed in PBMCs infected with BVDV alone, but not the cells treated with FTA alone or BVDV plus FTA compared to the controls at 48 and 72 h after infection (P = 0.0002 and P < 0.0001, respectively)." (PMID 27617959, 2016). "Blockade of CD4 before spinoculation inhibited upregulation of CTLA-4 and GITR during infection." (PMID 26482032, 2015). "In depth phenotypic characterization demonstrated an increase in the frequency of Tregs co-expressing CTLA-4 and the ecto-enzyme CD39 in CI patients during the late acute phase of HCV infection (p = 0.0491 vs pre-infection; p = 0.0104 vs SR and p = 0.0019 vs HD)." (PMID 23818845, 2013). "The role of CTLA4 SNPs in infection following renal transplantation has not been completely elucidated and needs to be studied in greater depth." (PMID 24015180, 2013). "Moreover, viral load was correlated with the expression of the inhibitory molecules CTLA-4 and PD-1, suggesting a vicious cycle where HIV-1 and immune alterations persist during the chronic phase of infection." (PMID 22276176, 2012). "FliC431–439-specific Tregs were found to down-regulate CTLA-4 and up-regulate GITR expression, as infection progressed from early to late time points to a similar extent in FliC431–439-specific compared with bulk Tregs at these same time points after infection." (PMID 20714351, 2010). "By extension, at later time points after infection (day 37) when CTLA-4 expression is down-regulated on Foxp3+ Tregs, no significant change in Salmonella bacterial burden or T cell activation occurred with CTLA-4 blockade." (PMID 20714351, 2010). "For example, in LCMV-infected mice, the disruption of CTLA-4 signaling fails to modify the course of infection or antiviral T cell responses in vivo, unlike PD-1 blockade." (PMID 19247441, 2009). "Interestingly, the more substantial upshift in CTLA-4 staining was seen on CD25– cells, and this change occurred later in the course of infection than the expansion in CD25+ cell numbers." (PMID 17563918, 2007). "Our results also indicate that in the vasospasm-positive (sVP+) group, CTLA-4 and PD-L1 levels remain consistently elevated regardless of the presence or absence of infection, supporting the interpretation that vasospasm itself is the primary driver of these changes." (PMID 40943153, 2025). "Thus, it is suggested that PCV2 single infection and PCV2 prior to PRRSV infection could increase the CTLA-4 expression." (PMID 36992486, 2023).
infection (continued). "There were no more than 20% of the cells as CTLA-4 SP after infection in all populations." (PMID 35720410, 2022). "Given that infection with HIV has been shown to lead to modulation of T cell phenotypic profiles, we next determined the effect of HIV infection on the total CD4 T cell expression profiles of BTLA, CTLA-4, and PD-1 in individuals with LTBI and with active TB, using a Boolean gating strategy." (PMID 31497018, 2019). "Interestingly, some mice that received mock infections did eventually reject their allografts under chronic immunosuppression with CTLA4-Ig, but did not reject their allografts under chronic immunosuppression with CTLA4-Ig and rapamycin." (PMID 29963060, 2018). "In addition, we showed that high expression of CTLA-4 and low levels of IL-2 prevented mTOR activation and Otub-1 protein expression, and maintained GRAIL expression, which inhibited T cell proliferation during the acute phase of the infection." (PMID 28114324, 2017). "This might indicate that the absence of co-stimulation during the acute phase of infection due to increased expression of inhibitory molecules, such as CTLA-4, which may allow GRAIL expression to be maintained via a blockade of mTOR activation." (PMID 28114324, 2017). "One of the major mechanisms for immunosuppression is hypothesized to be increased expression of immune regulatory checkpoints including PD-1, PD-L1, CTLA4 and BTLA, and targeting these negative regulators of immune responses has shown to improve host resistance to infections." (PMID 29135922, 2017). "To assess the effect of Ad5hr infection on CD4+ regulatory T cells, we evaluated the frequency of CD4+ Treg (Foxp3+/CD25hi) and a CD4+ Treg subset expressing CTLA4 (Foxp3+/CTLA4+/CD25hi) that is thought to be particularly immunosuppressive, as CTLA4 is required for suppression by Tregs." (PMID 25203111, 2014). "We decided to focus on CTLA-4 and PD-1/PD-L1 particularly because both of these inhibitory pathways have been extensively studied in chronic infections but a comparison of the two pathways during an acute infection was lacking." (PMID 22319445, 2012). "Thus, the CTLA-4 and PD-1/PD-L1 pathways seem to function very efficiently in BALB/c mice, maintaining the balance between immunity and immune pathology during the critical early stage of infection." (PMID 22319445, 2012). "Specific single nucleotide polymorphisms (SNPs), such as PTPN22 rs2476601 and CTLA4 rs3087243, are associated with infection-triggered CFS/ME, while other SNPs, such as IRF5 rs3807306 and TNF rs1799724, have decreased allele frequencies in CFS/ME patients who do not have infection-triggered onset." (PMID 39483544, 2024). "Immune checkpoint molecules including PD1, PDL1, CTLA4, LAG3, and IDO1 were significantly upregulated in the JBNU-22-N01-infected group compared with the negative control and VR2332 infection at 7 dpi." (PMID 40459260, 2025). "At 14 dpi, all infection groups showed almost identical upregulated mRNA expression profiles of PD1, PDL1, CTLA4, LAG3, and IDO1 compared with the negative control." (PMID 40459260, 2025). "In summary, infection but not model antigens was able to induce CD4+ T-cell cytotoxicity in vivo, and this phenotype was accentuated by administration of anti-CTLA4 antibody." (PMID 37161048, 2023). "Using experimental aerosol infection of mice with Mycobacterium bovis bacillus Calmette-Guérin (BCG), it was shown that inhibition of CTLA-4 by antibody did not enhance protection." (PMID 19609446, 2009). "The decrease of memory B cells, CD69+ and CD38+T cells, as well as the increase of PD-1+, CTLA-4+ of CD4+/CD8+T cells and double negative B cells, indicate that sustained immune responses against BA.5 infection may wane more rapidly in elderly populations." (PMID 40416973, 2025).
infection (continued). "Imperfect control of lymphocyte activity, due to SNPs of PTPN22, CTLA-4, BTLA, and some other elements of the immune response, makes it difficult to stop immune activity that is no longer needed after recovery from infection." (PMID 38792338, 2024). "In summary, during chronic ASCs with HBeAg-negative infection, CD4+ T cells and their subsets, including Th1, Th2, Th17, Tfh, and Treg cells, showed high expressions of immune checkpoint molecules (TIM-3, PD-1, CTLA-4, and LAG-3) and decreased the secretion of cytokines." (PMID 35572697, 2022). "M.tb-specific FoxP3+ T cells have been currently discussed to enrich in mice peripheral lymphoid nodes after infection with M.tb; those Treg-like cells were activated by expressing high amounts of cell surface CD25, CTLA-4, GITR, CD103, and ICOS, but not producing IFN-γ." (PMID 33977110, 2021). "Since T cells have been implicated in CS and CD28, CTLA4, and PD-L1 influence both innate and adaptive immune responses to infection, we asked whether the absence of CD28, CTLA4, or PD-L1 would affect the progression of CS in ocularly infected mice." (PMID 34281386, 2021). "For instance, CD69, CD160, CD44, LAG3, and CTLA-4 expression on day 7 is unaffected in the absence of AT1R following immunization, but here we showed that the expression of these proteins is reduced by day 6 following infection." (PMID 28261571, 2017). "Moreover, CTLA-4 expression levels of vaccine-induced CD4 and CD8 T cells reactive towards spike of the parental strain and the Omicron subvariants were similarly high irrespective of prior infection." (PMID 38594497, 2024).
hematological malignancies (51 papers, 2015 to 2026). "Recent studies have explored the relationship between CTLA-4 gene polymorphisms and susceptibility to hematologic malignancy." (PMID 39464701, 2024). "In this meta-analysis, we summarized the results of 13 relevant studies and highlighted the potential relationship between CTLA-4 gene polymorphisms and hematologic malignancies." (PMID 39464701, 2024). "The pooled odds ratio (OR) and its 95% confidence interval (CI) were used to determine the strength of the association between CTLA-4 polymorphisms and hematologic malignancy susceptibility." (PMID 39464701, 2024). "The pooled results indicated that CTLA-4 49A/G polymorphism was associated with hematologic malignancy risk under dominant model (AA vs. GA+GG: OR = 1.77, 95% CI = 1.56-2.02, P = 0.001)." (PMID 39464701, 2024). "Summary of meta-analysis of association of CTLA-4 319C/T (rs5742909) polymorphism and hematologic malignancy risk." (PMID 39464701, 2024). "Recent studies have reported an association between Cytotoxic T-lymphocyte antigen-4 (CTLA-4) polymorphisms and hematologic malignancy susceptibility, while the results remain inconsistent." (PMID 39464701, 2024). "ICIs prevent solid and hematological malignancies from evading the natural antitumor response by targeting programmed cell death protein-1 (PD-1) receptor/ligand on T cells and cytotoxic T-lymphocyte-associated antigen 4 (CTLA-4)." (PMID 37700240, 2023). "In recent years, therapeutic blockades of immune checkpoint pathways, particularly programmed death 1 (PD-1), PD ligand 1 (PD-L1), and cytotoxic T-lymphocyte associated protein 4 (CTLA-4), have become research hotspots in various hematological malignancies." (PMID 30050957, 2018). "CTLA-4 49A/G and 319C/T polymorphisms were associated with hematologic malignancy susceptibility." (PMID 39464701, 2024). "In conclusion, this meta-analysis suggests a significant association between CTLA-4 49A/G and CTLA-4 319C/T with hematologic malignancy risk." (PMID 39464701, 2024). "Ipilimumab-mediated CTLA-4 inhibition shows responses in about one-third of patients experiencing relapsed AML or other hematologic malignancies following allo-HCT, while maintaining a manageable safety profile." (PMID 39635535, 2024). "CTLA-4 is an immune checkpoint co-stimulatory protein that is commonly overexpressed in various solid and hematologic malignancies and serves to promote evasion of immune surveillance by inhibiting T-cell activation and proliferation." (PMID 37175780, 2023). "Immune checkpoint inhibitor therapies, specifically targeting programmed death 1 (PD-1) and cytotoxic T-lymphocyte-associated protein 4 (CTLA-4), have brought significant advancements in the treatment of hematological malignancies." (PMID 37374055, 2023). "Immune checkpoint blockade therapies, such as anti-programmed death 1 (PD-1) and anti-cytotoxic T-lymphocyte-associated protein 4 (CTLA-4), have provided new hope for the treatment of hematological malignancies." (PMID 36384564, 2022). "Antibodies targeting CTLA-4, PD-1, and PD-L1 are IC-blockade drugs approved for the treatment of various solid and hematological malignancies." (PMID 35164813, 2022). "During treatment of hematological malignancies with anti-CTLA-4 antibodies (most commonly Ipilimumab), the most common Grade 3 adverse events were diarrhea and fatigue." (PMID 35155232, 2022). "Immune-related adverse events (irAEs) frequently complicate treatment with immune checkpoint blockade (ICB) targeting CTLA-4, PD-1, and PD-L1, which are commonly used to treat solid and hematologic malignancies." (PMID 35740660, 2022). "CTLA4 and PD-1 have been demonstrated to play important roles in hampering T cell immunity against hematological malignancies and immune evasion of AML49–52." (PMID 33649342, 2021). "Antibodies targeting both the PD-1 and CTLA-4 pathways have shown efficacy in a variety of solid tumors and in some hematologic malignancies in clinical trials." (PMID 33649342, 2021).
hematological malignancies (continued). "Ipilimumab and tremelimumab are available cytotoxic T-lymphocyte-associated protein 4 (CTLA-4 or CD152) inhibitors, but with limited off-label use in pediatric hematologic malignancies." (PMID 33807678, 2021). "To date, the most encouraging clinical data that supports the importance of CTLA-4 pathway in AML comes from a phase I trial exploring the use of ipilimumab in patients with hematological malignancies relapsing post allo-HSCT." (PMID 32435621, 2020). "As of today, several HDACi have been approved by the FDA either as monotherapy or in combination with other drugs, such as with PD-1 or CTLA-4 checkpoint inhibitors, for the treatment of hematological malignancies and some solid tumors [see Ref." (PMID 29593742, 2018). "Currently, several trials have been initiated where azacitidine is combined with PD-1/PD-L1 or CTLA-4 checkpoint inhibitors in hematological malignancies and colorectal cancer." (PMID 29593742, 2018). "The pooled results indicated that CTLA-4 318T/C was not significantly related to hematologic malignancy risk in all models." (PMID 39464701, 2024). "This may be one reason that vorinostat is efficacious in treating advanced MF and other hematologic malignancies, as suppression of CTLA-4 likely promotes a more robust immune response against malignant tissues." (PMID 37175780, 2023). "Further, therapeutic blockade of immune checkpoints by blocking antibodies against CTLA-4 or PD-1 has been shown to produce a broad and beneficial clinical outcome in hematological malignancies, as well as improving the potency of CAR-T-cell or TCR-T-cell-based therapies." (PMID 28116322, 2017). "In hematological malignancies, common immune checkpoint targets are reported mainly include PDCD1, IDO1, PD-L1, LAG3, and CTLA-4." (PMID 36061194, 2022). "Here, we review the preclinical and clinical advances of CTLA-4 and PD-L1/PD-1-based ICB and CD19-specific CAR-T cell therapy in hematologic malignancies." (PMID 31186046, 2019). "Inhibition of CTLA4/B7 and PD1/PDL1 signaling is now also being investigated and already successfully applied to various hematologic malignancies." (PMID 29564225, 2018). "Unlike in many solid tumors, CD28 and CTLA-4 are innately expressed and play important biological roles in many hematological malignancies." (PMID 31195368, 2019). "TIM-3, TIGIT, and CTLA-4 upregulation in CD8+ T cells with exhaustion features has been reported in chronic lymphocytic leukemia (CLL), AML, and post-allogenic HSCT B-ALL relapse, and targeting these exhaustion markers improved the outcome of hematological malignancies." (PMID 36901957, 2023).
endocrinopathies (29 papers, 2015 to 2025). "In general, combination therapy (anti-CTLA-4 plus anti-PD-1/PD-L1) had a stronger association with endocrinopathies than monotherapy (ROR: 2.8, 95% CI: 2.5–3.1)." (PMID 32507965, 2020). "Higher rates of endocrine disorders are associated with anti-PD-1 therapy, whereas gastrointestinal toxicities are more common with CTLA-4 inhibitor administration." (PMID 31708780, 2019). "Additionally, another analysis based on FAERS database also support our results suggesting anti-CTLA-4 treatment was associated with a higher reporting frequency of endocrine disorders when compared with anti-PD1/anti-PD-L1 treatment (ROR = 1.60, 95%CI 1.46–1.75)." (PMID 31694698, 2019). "In this review, 11–30% of patients developed endocrinopathies, with the highest incidence and severity observed under combined or sequential anti-CTLA-4 and anti-PD-1/PD-L1 regimens." (PMID 41301042, 2025). "The coexistence of these two distinct endocrinopathies likely reflects a cumulative immune-mediated effect triggered by the simultaneous blockade of both CTLA-4 and PD-1 pathways." (PMID 40932982, 2025). "Prior research has indicated that the onset of endocrinopathies occurs within a timeframe of 9 to 12 weeks following the administration of CTLA-4 and within an interval of 4 to 18 weeks following the administration of anti-PD-1." (PMID 37779728, 2023). "In this study, we were able to show that 20% of the patients treated with ICI will experience endocrinopathies, with a higher incidence and grade in the CTLA-4-based regimen." (PMID 37271776, 2023). "Clinically significant endocrinopathy occurs in less than 10% of patients treated with CTLA-4 inhibitors, but in patients treated with anti-PD -1/PD-L1, it appears to be higher." (PMID 34236546, 2021). "Combination therapy-related endocrinopathies covered endocrine ADRs induced by anti-CTLA-4 monotherapy and anti-PD-1/PD-L1 monotherapy." (PMID 32507965, 2020). "Our report demonstrates a rare endocrinopathy as a complication of combined PD-1 and CTLA-4 blockade." (PMID 30791949, 2019). "Endocrinopathies and inflammatory pathologies induced by PD-1 / PDL-1 or CTLA-4 blocking agents are frequently reported in both monotherapy and combinatorial therapies." (PMID 36158826, 2022). "Onset time of common endocrinopathies differed between different ICI therapies, typically within 12 weeks in anti-CTLA-4 monotherapy but diffusely ranging from 0 to 48 weeks in anti-PD-1 monotherapy." (PMID 32507965, 2020). "The total incidence of endocrinopathies was 11.8%, 13.4% due to anti‐PD1/PDL1, 5% due to anti‐CTLA4, and 18.5% due to sequential and/or combination treatment." (PMID 31518074, 2019). "However, the onset time of endocrinopathies varied between different ICI therapies, typically occurring within 12 weeks for anti-CTLA-4 monotherapy but ranging from 0 to 48 weeks for anti-PD-1 monotherapy." (PMID 39616333, 2024).